CADM1 (cell adhesion molecule 1)
Diseases named in the same sentence as CADM1 in open-access papers (continued):
Sharing a sentence is not in itself a finding about the gene and the disease.
melanoma (22 papers, 2015 to 2025). A malignant, usually aggressive tumor composed of atypical, neoplastic melanocytes. "Together, these data demonstrate that CADM1 levels are decreased as melanoma progresses and high levels of CADM1 are associated with better clinical outcomes." (PMID 30911007, 2019). "In cutaneous solid tumors, the CADM1 promoter is highly methylated in cutaneous melanoma and is also associated with the advance of the tumor stage and disease-related survival methylation, suggesting that CADM1 is an indicator for poor prognoses of melanoma." (PMID 33419290, 2020). "Importantly, tissue microarray analysis and clinical data from TCGA indicate that CADM1 expression is inversely associated with melanoma progression and positively correlated with better overall survival in patients." (PMID 30911007, 2019). "Furthermore, high CADM1 expression in patient samples was linked to less aggressive melanomas and associated with improved progression free and overall survival." (PMID 30911007, 2019). "We next questioned whether CADM1 expression was associated with a better prognosis in melanoma patients." (PMID 30911007, 2019). "LNMAT1 depletion decreased EZH2 binding and H3K27me3 of the CADM1 promoter which results in CADM1 upregulation, and silencing CADM1 expression partially rescues inhibitory effects on melanoma cell migration and invasion induced by LNMAT1 depletion." (PMID 37325482, 2023). "CADM1 overexpression inhibits invasion and migration in melanoma and induces the death of tumor cells under non-adhesive conditions." (PMID 34395444, 2021). "Solid cutaneous malignancies, such as cutaneous squamous cell carcinoma and malignant melanoma, reduce their CADM1 expression to promote the invasion and metastasis of the tumor." (PMID 33419290, 2020). "The CADM1-transfected melanoma cells are significantly suppressed in their growth in vitro, and the ability of invasion is also reduced." (PMID 33419290, 2020). "There is a significant reduction in the expression of CADM1 in advanced melanoma compared to dysplastic compound melanocytic nevi." (PMID 33419290, 2020). "As a relationship with cutaneous malignancies, melanoma and squamous cell carcinoma are also candidate diseases for CADM1-targeted therapy." (PMID 33419290, 2020). "MicroRNA-214 enhances the process of epithelial-mesenchymal transition EMT in melanoma by the downmodulation of CADM1, which is recovered by miR-214 inhibitor, leading to the suppressive effect against EMT processes." (PMID 33419290, 2020). "The average expression levels of CADM1 mRNA and protein in melanoma are significantly decreased compared with dysplastic nevi lesions and normal skin." (PMID 33419290, 2020). "Among solid tumors, melanoma and squamous cell carcinoma have been known to be the diseases in which CADM1 can be utilized as a biomarker." (PMID 33419290, 2020). "Increased expression of CADM1 results in a significant inhibition of motility and invasiveness of melanoma cells." (PMID 33419290, 2020). "We found that CADM1 expression in melanoma reduces migratory and invasive potential and potently induces cell death in non-adherent cells." (PMID 30911007, 2019). "Using melanoma as a model system, we demonstrate that CADM1 is a critical negative regulator of metastatic traits." (PMID 30911007, 2019). "CADM1 was inversely associated with TWIST1 across melanoma genotypes and TWIST1 occupied the proximal CADM1 promoter." (PMID 30911007, 2019). "We found that TWIST1 acts to repress CADM1 levels and suppression of CADM1 appears to enhance traits needed for metastatic dissemination of melanoma." (PMID 30911007, 2019). "Together, these data demonstrate that CADM1 suppresses migratory and invasive potential, as well as induces cell adhesion and aggregation in human melanoma cells." (PMID 30911007, 2019).
melanoma (continued). "Our data support that CADM1 is acting as a suppressor of metastatic-like traits in melanoma cells and that CADM1 expression is correlated with an increase of OS in melanoma patients." (PMID 30911007, 2019). "We further explored the effect of CADM1 expression on melanoma invasiveness by utilizing collagen-embedded 3D spheroid assays that models dermal outgrowth." (PMID 30911007, 2019). "Increased expression of CADM1 resulted in significant inhibition of motility and invasiveness of melanoma cells." (PMID 30911007, 2019). "In matrigel-coated Boyden chambers, CADM1 overexpression suppressed the invasiveness of melanoma cells, while CADM1 knockdown increased melanoma cell invasion." (PMID 30911007, 2019). "We showed that CADM1 suppresses invasive and migratory potential of melanoma cells, and potently induces cell death when melanoma cells are cultured in non-adherent conditions." (PMID 30911007, 2019). "Compared to LacZ expressing cells, CADM1 expression in 1205LuTR suppressed the invasive depth of the melanoma." (PMID 30911007, 2019). "Some studies show that CADM1 could be used as a biomarker for cervical lesions and malignant melanoma." (PMID 36523593, 2022). "The survival of melanoma is significantly decreased in reduced expression of CADM1 patients with melanoma or harboring methylated CADM1, indicating that the epigenetic modification of CADM1 by hypermethylation is also an important factor in the pathogenesis of melanoma." (PMID 33419290, 2020). "It activates cell migration and the invasion of malignant melanoma by suppressing CADM1 expression." (PMID 33419290, 2020). "The expression of CADM1 is reduced in melanoma above 1 mm in thickness." (PMID 33419290, 2020). "Human melanoma cell lines were transduced to inducibly express CADM1 or CADM1 shRNA constructs." (PMID 30911007, 2019). "In melanoma disease progression, CADM1 may act as a barrier to metastasis by inhibiting the invasiveness, motility, and inducing cell death in non-adherent conditions." (PMID 30911007, 2019). "Melanoma spheroids expressing CADM1 invaded significantly less than LacZ-expressing counterparts." (PMID 30911007, 2019). "Together, these data suggest that CADM1 exerts tumor suppressive functions in melanoma by reducing invasive potential and may be considered a biomarker for favorable prognosis." (PMID 30911007, 2019). "In MM, it was reported that CADM1 expression was significantly downregulated in melanoma tissues." (PMID 31334110, 2019). "CADM1 has also been found differentially expressed in melanocytic lesions and had the potential to contribute as an auxiliary tool to the differential diagnosis between nevi and melanomas." (PMID 30153287, 2018). "Notably, the expression of cell adhesion molecule 1 (CADM1) was decreased in melanoma cells." (PMID 40861221, 2025). "Nonetheless, the oncogenic role of miR-1246 has been reported in melanoma by conferring resistance to BRAF inhibitors or enhancing migration and invasion through the adhesion molecule CADM1 in hepatocellular cancer." (PMID 36551682, 2022). "MiR-214 silences cell adhesion molecule 1 (CADM1), a known tumor suppressor, thus leading to higher migration and invasion of melanoma cells and EMT promotion, in which miR-214 contributes to annoikis resistance and subsequently to extravasation." (PMID 35884446, 2022). "In melanoma, TWIST1 directly inhibits CADM1 expression by interacting with the E-box in the CADM1 promoter region and promotes EMT phenotype conversion, which aggravates migration and invasion of melanoma cells." (PMID 34395444, 2021). "Recent studies identified that CADM1 was closely related to the development or regulation of skin cancers, such as SCC, malignant melanoma, adult T-cell leukemia/lymphoma, mycosis fungoides, Sézary Syndrome, and Merkel cell carcinoma." (PMID 34064472, 2021). "In melanoma, TWIST1 can directly act on the CADM1 promoter region to inhibit the expression of CADM1 and promote tumor metastasis." (PMID 34395444, 2021).
melanoma (continued). "A human melanoma panel containing radial growth phase, vertical growth phase (VGP), and metastatic cell lines were assayed for CADM1 expression." (PMID 30911007, 2019). "In mutant BRAF melanoma cells, flow cytometry revealed that PLX4720 induced an increase of surface exposed CADM1." (PMID 30911007, 2019). "In addition to miR-214/CADM1 and miR-182/RECK, recent studies have demonstrated that the exosomal miR-29c-3p derived from M1 macrophages inhibits the invasiveness of melanoma cells through ectonucleotide pyrophosphatase/phosphodiesterase 2 (ENPP2)." (PMID 40861221, 2025). "It has been demonstrated that LNMAT1 promotes migration and invasion of melanoma in vitro and in vivo by cooperating with EZH2 to inhibit the expression of cell adhesion molecule 1 (CADM1), a recognized tumor suppressor that inhibits the expression of MMP-2 and MMP-9 matrix metalloproteinases." (PMID 37325482, 2023). "Together these data implicate CADM1 as a suppressor of melanoma cell viability in non-adherent conditions." (PMID 30911007, 2019). "Augmented CADM1 expression significantly increased cell death in non-adherent conditions, and reduced the invasive and migratory potential of melanoma cells." (PMID 30911007, 2019). "Notably, endogenous levels of CADM1 were reduced when melanoma cell lines were cultured in non-adherent conditions." (PMID 30911007, 2019). "Consequently, we performed microarray analysis to elucidate the differential roles of CADM1 in melanoma cells in adherent vs. non-adherent conditions." (PMID 30911007, 2019).
ovarian carcinoma (18 papers, 2012 to 2025). A malignant neoplasm originating from the surface ovarian epithelium. "Loss of CADM1 expression predicted poor prognosis and the development of esophageal cancer and ovarian cancer." (PMID 34497766, 2021). "Similarly to Cadm1, this gene is also frequently silenced by promoter hypermethylation and/or loss of heterozygosity in several tumors including ovarian cancer and gliomas." (PMID 23029096, 2012). "Thus, CADM1 can be a diagnostic indicator and a potential therapeutic target for ovarian cancer." (PMID 34395444, 2021). "CADM1 overexpression potentially inhibits the migration and invasion of ovarian cancer cells by regulating the upstream regulatory factor C4b-binding protein (C4BPA) and the PI3/Akt/mTOR signaling pathway." (PMID 38481252, 2024). "Thereinto, CADM1 has been comprehensively studied, and its inhibitory effect on tumor proliferation and invasion has been reported in ovarian cancer, bladder cancer and other tumors." (PMID 38515057, 2024). "A similar study in ovarian cancer cells described the downregulation of the CADM1-targeting miR-486, which saw reduced cell viability, proliferation, and an increased proportion of cells in G0/G1 arrest." (PMID 36316307, 2022). "Regulation of C4BPA can inhibit the PI3K/Akt/mTOR signaling pathway induced by the overexpression of CADM1, thereby affecting the migration and invasion of ovarian cancer cells." (PMID 36177001, 2022). "For example, the low expression of CADM1 in OV has been reported to inhibit the proliferation and migration of ovarian cancer cells through the PI3K/Akt/mTOR pathway." (PMID 33763357, 2021). "In ovarian cancer, CADM1 overexpression upregulates genes like LXR/RXR, IGF1, IFI44L, and C4BPA, in addition to inhibiting the PI3K/Akt/mTOR pathway as well as affecting the downstream (APP, EDN1, TGFBI, and Rap1A) expression." (PMID 34395444, 2021). "CADM1 expression in ovarian cancer tissues and cell lines is also significantly low." (PMID 34395444, 2021). "Furthermore, CADM1 overexpression inhibits metastasis and migration in ovarian cancer cells." (PMID 34395444, 2021).
non-small cell lung carcinoma (17 papers, 2005 to 2023). A group of at least three distinct histological types of lung cancer, including non-small cell squamous cell carcinoma, adenocarcinoma, and large cell carcinoma. "The CADM1 gene was originally identified as a tumor suppressor gene in non-small cell lung cancer, and the loss of CADM1 expression is associated with a poor prognosis and metastasis in various types of solid cancers." (PMID 30837480, 2019). "It is originally identified as a tumor suppressor gene TSLC1 in human non-small cell carcinoma and a growing body of researches show that CADM1 has a regulatory effect on the progression of tumors." (PMID 37814227, 2023). "miR-486-5p in non-small cell lung cancer (NSCLC) targets the CADM1/tight junction axis in vascular endothelial cells to promote metastasis of non-small cell lung cancer cells." (PMID 37602326, 2023). "CADM1 gene on chromosome fragment 11q23.2 was originally identified as a tumor suppressor gene in non-small-cell lung cancer, which was confirmed in nude mice." (PMID 34395181, 2021). "We have previously identified Cell adhesion molecule 1 (CADM1) as a tumor suppressor in non-small cell lung cancer (Gene ID: 23705)." (PMID 25780926, 2015). "By contrast, CADM1 expression is often lost by promoter methylation in various invasive cancers, including non-small cell lung cancer, breast cancer and pancreatic cancer." (PMID 25780926, 2015). "Studies in nude mice have demonstrated that re-expression of CADM1 suppresses in vivo tumorigenicity of non-small cell lung cancer and nasopharyngeal carcinoma cell lines." (PMID 22553910, 2012). "Interestingly, MPP2 mislocalization has been observed in two non-small-cell lung cancer (NSCLC) cell lines, NCI-H596 and SK-LU-1, characterized by a loss of CADM1 and 4.1B expression." (PMID 33114686, 2020). "Although CADM1 functions as a tumor suppressor in non-small cell lung cancer (NSCLC) and is downregulated in many solid tumors, its expression is significantly upregulated in the context of infection with the oncogenic retrovirus HTLV-1, and associated ATL tumor cells." (PMID 29698475, 2018). "CADM1, also known as TSLC1 (Tumor Suppressor in Lung Cancer 1), was first found in human chromosome 11q23.2 as a new suppressor gene when exploring correlation between human non-small cell lung cancer and CADM1 through functional experiments." (PMID 29228687, 2017).
hepatocellular carcinoma (16 papers, 2014 to 2024). A malignant tumor that arises from hepatocytes. "The lower expression of CADM1 is related with the development of hepatocellular carcinoma." (PMID 33419290, 2020). "Recent study has shown that CADM1 could regulate the G1/S transition and represses tumorigenicity through the Rb-E2F pathway in hepatocellular carcinoma." (PMID 30153287, 2018). "MiR-194 inhibits CADM1 protein level expression in hepatocellular carcinoma (HCC) by inhibiting mRNA translation of CADM1, and promoting proliferation, invasion, migration, and cell cycle progression of HCC cells by inhibition of CADM1." (PMID 33419290, 2020). "Moreover, the 5′tRF-Gly intensifies cell growth, migration, and invasion in hepatocellular carcinoma (HCC) by restraining CEA cell adhesion molecule 1 (CEACAM1)." (PMID 39659673, 2024).
lung adenocarcinoma (14 papers, 2005 to 2024). A carcinoma that arises from the lung and is characterized by the presence of malignant glandular epithelial cells. "Specifically, it intensifies the progression of lung adenocarcinoma by targeting CADM1, promotes the progression of prostate cancer by targeting GRIM-19, and suppresses the proliferation and invasion of osteosarcoma by targeting STMN1." (PMID 38140218, 2023). "In lung adenocarcinoma, CADM1 is involved in the Hippo pathway and regulates cell proliferation and contact inhibition." (PMID 34395444, 2021). "CADM1 expression is relatively lower in metastatic breast cancer and lung adenocarcinoma patients than in patients with non-invasive cancer." (PMID 31334110, 2019). "We next compared our SE score to a leading gene expression based prognostic indicator for lung adenocarcinoma, the expression of the gene CADM1, which was recently found to be a superior prognostic indicator to many others in the literature." (PMID 25793737, 2015). "Moreover, CADM1 is downregulated in lung adenocarcinomas as well and is highly correlated with shorter survival." (PMID 34395444, 2021). "Thus, membrane CADM1 detection can be used to diagnose and determine the prognosis of lung adenocarcinoma." (PMID 34395444, 2021). "In this tumor PDS, the differential expression of the CADM1 and the MMP1 genes was reversed compared to that observed across the TCGA lung adenocarcinoma analysis." (PMID 38067281, 2023). "Clinically, co-expression of CADM1 and LATS2 on the cell membrane of cancer cells predicts good prognosis of lung adenocarcinoma." (PMID 32527032, 2020). "Intriguingly, there are also a few exceptions whereby CADM1 is overexpressed in select tumor types, such as ATL and lung adenocarcinoma." (PMID 29698475, 2018). "CADM1/TSLC1, also called IGSF4-3, was first identified by Murakami in the study of lung adenocarcinoma A549 cell lines through functional complementary methods for determining new tumor-suppressor gene." (PMID 26880895, 2016). "In addition, membrane coexpression of CADM1 and LATS2 is highly correlated with the histological type of lung adenocarcinoma." (PMID 34395444, 2021). "We found that the SE score improved over stage Ia/b alone in a meta-analysis across 765 stage I lung adenocarcinomas (SE score+stage vs stage: p = 0.025), whereas CADM1 expression made no improvement over stage Ia/b (CADM1 expression+stage vs stage: p = 0.13)." (PMID 25793737, 2015).